CCND1 (cyclin D1)
Diseases named in the same sentence as CCND1 in open-access papers (continued):
Sharing a sentence is not in itself a finding about the gene and the disease.
melanoma (continued). "CCND1 copy number increase is known to occur more commonly in acral melanomas than in melanomas in other cutaneous sites." (PMID 34225728, 2021). "RGP melanoma commonly shows loss of function mutations in tumor suppressor genes and cell cycle regulator genes like CCND1, which further perpetuates melanoma growth." (PMID 34769150, 2021). "Using FISH, 29 acral melanomas (29/61, 47.5%) showed increase in the CCND1 copy number, including 8 (8/61, 13.1%) which showed low-level increase in the CCND1 copy number and 21 (21/61, 34.4%) with high-level increase in the CCND1 copy number." (PMID 34225728, 2021). "CCND1 gene amplifications affect about 30% of acral melanomas, 11% of lentigo maligna melanomas, and 6% of superficial spreading melanomas." (PMID 34571969, 2021). "In this sense, the present study showed that CCND1/cyclin D1 upregulation is a common molecular oncogenic alteration in melanomas that probably favors the growth and expansion on cutaneous primary melanomas." (PMID 33804108, 2021). "Although no studies have been designed to provide direct evidence of the other emerging functions of cyclin D1 in melanoma, some studies have observed an increase in cell migration after the activation of upstream regulators of cyclin D1 in melanomas." (PMID 33804108, 2021). "The prevalence of the amplification of CCND1 is controversial and the frequency differs among melanoma types, with an established higher detection rate in acral melanoma." (PMID 34071228, 2021). "In uveal melanomas, CCND1/cyclin D1 upregulation is observed in 14.41% of cases, while in mucous melanomas, appeared in 42.33% of cases, with melanoma of the oral cavity presenting the highest frequency—80.05% of cases." (PMID 33804108, 2021). "Our results are consistent with the possibility CCND1 copy number increase induce high cyclin D1 expression and promote progression in acral melanomas with high-level CCND1 copy number increase." (PMID 34225728, 2021). "Based on whole-exome sequencing and RNA-sequencing profiling, CCND1 gain was detected in patients with melanoma resistant to anti-PD-1 immunotherapy." (PMID 33923996, 2021). "Conversely, proliferation indexes Ki67, cyclin D1, and Rb levels were upregulated in melanoma, whereas P16 expression was notably decreased." (PMID 34912899, 2021). "The cyclin D1 protein expression level correlates positively with the CCND1 copy number in acral melanomas with high-level CCND1 copy number increase (P = 0.038)." (PMID 34225728, 2021). "CCND1, which encodes for the Cyclin D1, protein has been shown to be amplified in BRAF-mutated and wild type melanomas." (PMID 34066022, 2021). "Inhibition of CDK4/6, or likewise knocking out Cyclin D1 or overexpressing p16INK4A, leads to increased PD-L1 expression in numerous cell lines and preclinical tumor models, including B16 melanoma." (PMID 34025662, 2021). "In our opinion, it is advisable to expand the knowledge about the meaning and true value of immunolocalization of cyclin D1 in the cytoplasm in melanoma." (PMID 33804108, 2021). "Cyclin D1 protein overexpression was assessed by 21 studies in 1473 melanomas (range: 7–245); CCND1 gene amplification was also analyzed by 22 studies in 2096 melanomas (range: 6–514)." (PMID 33804108, 2021). "Alterations in the CDKN2A pathway in melanomas can occur due to either copy number changes (deletions of CDKN2A, the amplification of CCND1, and the amplification of CDK4/6), mutations in CDKN2A or CDK4/6, and promoter hypermethylation of CDKN2A." (PMID 34831002, 2021). "In acral melanomas with low-level CCND1 copy number increase, the median IHC score was 25% (range: 3–90%)." (PMID 34225728, 2021). "Alterations in CDKN2A and in CCND1 are present in NRAS mutant melanomas in 70% and 10% of cases, respectively." (PMID 34831002, 2021). "Increased expression of cyclin D1 has also been reported in up to 62% of primary melanomas, while being minimal in melanocytic naevi." (PMID 32374893, 2020).
melanoma (continued). "AG at this concentration also significantly downregulated CCND1 expression already after 6 h in the majority of melanoma cell lines." (PMID 32466509, 2020). "CCND1 alone can accelerate the resistance in BRAF-mutant melanoma and is intensified when there is both cyclin D1 overexpression along with a cyclin dependent kinase-4 (CDK4) mutation." (PMID 32092958, 2020). "CCND1 mRNA level was further reduced to about 50% of control (p ≤ 0.05) after 22 h in all melanoma cell lines, or even below 50% of control as in DMBC22 cells." (PMID 32466509, 2020). "Oncogenomic studies indicate that somatic CNV of some genes is involved in melanoma progressions, such as mutated gene amplifications in CCND1, CDK4, and TERT, of which the CNV status also has been reported in Chinese melanomas." (PMID 32083130, 2020). "In melanoma, the CCND1 amplification rate is 11%, and this increases to 17% in BRAF V600E melanoma, suggesting a critical role for CCND1 in BRAF-mutated melanoma patients." (PMID 32413516, 2020). "Accordingly, protein levels of cyclin D1 were substantially reduced in melanoma cell lines exposed to AG." (PMID 32466509, 2020). "A retrospective study of melanoma also showed that 30 out of 56 patients with innate resistance to anti-PD-1 therapy presented with CCND1 amplification." (PMID 32903763, 2020). "In line, we identified the transcription factor AP-1 and its target Cyclin D1, both shown to be affected by HuR in other cancer types, as targets of HuR regulation in melanoma cells." (PMID 32455577, 2020). "XL888 inhibited cell proliferation also in melanoma cells with intrinsic and acquired resistance to BRAF inhibitors that were dependent on different mechanisms including either overexpression of cyclin D1, PDGFR-β or COT, or NRAS mutation." (PMID 31659567, 2020). "Investigating the stepwise development of melanoma from in‐situ to invasive lesions, we found statistically significant differences in epidermal cyclin D1 expression between in‐situ and invasive melanomas." (PMID 32374893, 2020). "Cinobufagin decreases LEF1 expression in a dose-dependent manner and Wnt/β-catenin target genes such as Axin-2, cyclin D1, and c-Myc in melanoma cell lines." (PMID 32933177, 2020). "Prompted by preclinical results, we investigated cyclin D1 protein and Ki‐67 expression in in‐situ, metastatic and non‐metastatic thin melanomas." (PMID 32374893, 2020). "Cyclin D1 overexpression is sufficient to increase melanoma BRAFi resistance but this phenomenon is even more enhanced when cyclin D1 and CDK4 are concurrently overexpressed." (PMID 32605090, 2020). "We found an increased expression of cyclin D1 in invasive thin melanomas compared to in‐situ melanomas, which supports a potential role of this protein in early invasion in melanoma, as suggested by preclinical findings." (PMID 32374893, 2020). "We compared the differences in CCND1 amplification between the acral and cutaneous groups of melanoma and showed that CCND1was more amplified in the acral group." (PMID 32393283, 2020). "Epidermal cyclin D1 expression was significantly higher in thin invasive than in in‐situ melanoma (P = 0.003)." (PMID 32374893, 2020). "Lumican overexpression decreases subcutaneous primary melanoma tumor growth in vivo, with a concomitant decrease of cyclin D1 expression as well as a decrease in the number of lung metastatic nodules in which an increase of tumor cell apoptosis was observed." (PMID 32548117, 2020). "They found a higher rate of cyclin D1 expression in invasive and in‐situ melanoma compared with benign melanocytic lesions." (PMID 32374893, 2020). "When analysing melanoma subtypes, epidermal cyclin D1 expression appeared to be increased in SSM compared to LMM in univariate analysis (P = 0.02)." (PMID 32374893, 2020). "In contrast, a significantly higher percentage of cyclin D1‐positive tumour cells was found in thin invasive melanoma compared to MIS (P = 0.003)." (PMID 32374893, 2020).
melanoma (continued). "The effects of 4d on the cell cycle regulatory proteins p21, p27, and cyclin D1 in 518A2 melanoma cells were investigated." (PMID 30658435, 2019). "We showed that, as expected, a larger decrease of the cyclin D1 expression in (Bu3Sn)4TPPS-treated melanoma cells blocked in the G0/G1 phase compared to the cells treated with (Bu2Sn)2TPPS and blocked in G2/M phase." (PMID 31801187, 2019). "GAS5 knockdown increases melanoma cell proliferation by inducing Cyclin D1, CDK4, and p27 expression and inhibiting apoptosis via increasing Bcl-2 expression." (PMID 31500396, 2019). "G6PD status in melanoma cells is positively correlated with the expression of the cell cycle proteins, including cyclin D1 and cyclin E." (PMID 31500396, 2019). "B-RAF regulates p27 mRNA abundance, independently of cyclin D1, and mutations of B-RAF are implicated in 70% of melanomas." (PMID 29423113, 2018). "In our melanoma model, PRL3 expression was associated with enhanced cancer growth in parallel with increased cyclin D1 levels." (PMID 30157875, 2018). "Our group previously evidenced that 13.6% of patients with multiple primary melanomas carry a CCND1 gene amplification, with its higher incidence in subsequent lesions rather than in the primary ones." (PMID 29492214, 2018). "hMELTs are immortalized with both hTERT and CDK4R24C, and prior studies establish the ability of constitutive CDK4/Cyclin D1 activity to drive MAPK-independent melanoma growth." (PMID 29875996, 2018). "Indicative for a ‘proliferative’ phenotype, CCND1 expression was also up-regulated and the melanoma cell numbers increased more over 3 days on stiffer matrix." (PMID 29545604, 2018). "This heterogeneity in gene alteration distribution was somehow confirmed in the current study; CCND1 amplification was observed in 25% of cell lines deriving from both primary and metastatic lesions but in 6% only of the in vivo melanoma human tissues." (PMID 29492214, 2018). "The scenario of genetic alterations contributing to melanoma gene signature was completed by somatic CNVs, such as gene amplifications in CCND1, CDK4, KIT, MITF, and TERT as well as gene deletions in CDKN2A and PTEN." (PMID 30218391, 2018). "Accordingly, the inhibition of PPARγ by GW9662 reverted the effects on cell cycle modulators (p27, p21, Cyclin D1 and cyclin E) promoted by αMSH in both melanoma cell lines." (PMID 29020973, 2017). "Notch-1 promoted melanoma progression by inducing β-catenin, which in turn regulated cyclin D1 expression." (PMID 28977931, 2017). "MITF regulates the expression of numerous genes involved in the regulation of cell proliferation, such as B-cell lymphoma 2 (BCL2), cyclin-dependent kinase 2 (CDK2), cyclin D1, and p21, and promotes cell proliferation in melanocytes and melanomas." (PMID 28880216, 2017). "Because CCND1 is transcriptionally regulated by MITF, wogonin was presumed to inhibit CCND1 expression in human melanoma cells by downregulating MITF." (PMID 28182699, 2017). "Vitamin D3 mediated-arrest of cell proliferation and modulation of the expression repertoire of p21, p27, cyclin-D1 and likely of other cell-cycle key regulatory molecules, seem to be common biological events in melanoma experimental models used in this study." (PMID 28074906, 2017). "We find that itraconazole increases Gli-3, Axin-1 expression but decreases Gli-1, Gli-2, Axin-1, β-catenin, Wnt3A and Cyclin D1 expression in both melanoma cell lines when compared with untreated cells." (PMID 28212537, 2017). "Cell-cycle arrest in G1 phase, induced by 1α-OH-vitD3 in IR6 melanoma cell line correlated with an increased expression of the cyclin-dependent kinase inhibitors p21 and p27, and down-regulation of cyclin-D1." (PMID 28074906, 2017). "To evaluate the role of cyclin D1 overexpression, in BrafV600E/Perk+/- tissue, we deleted one allele of CCND1 and deletion completely abrogated melanoma genesis." (PMID 27977682, 2016).
melanoma (continued). "Dysregulated Wnt/β-catenin signaling pathway and subsequent up-regulation of β-catenin-driven downstream targets c-myc, survivin, and cyclin D1, and MMPs has been detected in a wide range of tumor types, including melanoma." (PMID 26968952, 2016). "Transcriptional activation followed by the nuclear translocation of β-catenin is a hallmark of Wnt signaling and is responsible for the transcription of cell growth regulatory genes including c-myc, cyclin D1, and survivin in melanoma cells." (PMID 26968952, 2016). "For example, downregulation of miR-15a, which is observed in several cancers including melanoma, led to an overexpression of several oncogens, such as Bcl-2, Cyclin D1, and Mcl-1." (PMID 26631117, 2015). "c-Jun has well-recognized roles in regulating both proliferation and apoptosis, but in melanoma it is thought to function downstream of ERK by promoting transcription of cyclin D1, a positive regulator of the G1-S cell cycle transition." (PMID 25814555, 2015). "At the meantime, cyclin D1, a mTORC1-regulated gene, was downregulated by VS-5584 in the two melanoma cell lines." (PMID 26204252, 2015). "Like sorafenib, oral administration of fisetin monotherapy significantly inhibited the tumor growth of BRAF-mutated melanoma cells in nude mice by inhibiting tumor cell proliferation markers (PCNA, Ki67 and cyclin D1)." (PMID 26299806, 2015). "The cyclin D1-encoding gene, CCND1, is targeted by miR-193b in hepatocellular carcinoma 10, melanoma 11, and pancreatic cancer." (PMID 26129688, 2015). "CCND1 has focal gains in 4 cell lines (CNS:SF_295, ME:SK_MEL_28, ME:SK_MEL_5, RE:TK_10) including 2 melanomas." (PMID 24670534, 2014). "Let-7b is significantly downregulated in primary melanomas compared to benign nevi, inhibits cyclin D1 in melanoma cells, and inhibits cell cycle progression and anchorage-independent growth when overexpressed in melanoma cells." (PMID 24047116, 2013). "Cyclin D1 silencing triggers a G1/S cell cycle arrest in vitro and leads to inhibition of melanoma growth in vivo." (PMID 24416617, 2013). "Elevated cyclin D1 gene expression in melanoma cells revealed that cyclin D1 was the key protein promoter of A375 cell proliferation and its overexpression can cause cell proliferation out of control which promotes tumor malignancy." (PMID 23693134, 2013). "The JNK pathway can be activated by ERK in a feedback loop and both pathways can activate cyclin D1 which is a positive regulator of cell cycle progression in melanoma cells." (PMID 23965971, 2013). "Gene amplification of chromosome 11p13 containing the CCND1 locus and enhancing cyclin D1 expression has been observed in melanoma cell and particularly in acral (44,4%), lentigo malignant (10,5%), and sinonasal melanomas (62,5%)." (PMID 24416617, 2013). "Copy number change at locus 11q13 cyclin D1 has been described in melanomas and it is strictly related to prognosis." (PMID 22770229, 2012). "Like Mitf, CYCLIN D1 has more than one miRNA validated as promoting its repression in melanoma cells." (PMID 21860617, 2012). "The consequence of the miR-let7b repression in melanoma cell line was the same as showen in the studies already reported about CYCLIN D1 and the same miRNA, that is, proliferation and colony formation reduction." (PMID 21860617, 2012). "As discussed by authors, these findings suggest a critical role for cyclin D1 in melanoma pathology, and illustrate how melanoma progression is meticulously and dynamic coordinated." (PMID 22110486, 2012).
melanoma (continued). "In one study of melanomas arising at chronic sun damaged sites CDK4 and CCND1 were implicated as independent oncogenes in melanomas without mutations in BRAF or N-RAS." (PMID 25562798, 2012). "In a study of Cyclin D1 role in melanoma progression it was showed that a considerable number of tumors had its expression raised independently of copy number amplification." (PMID 21860617, 2012). "Amplification of the CCND1 gene resulting in cyclin D1 over-expression has been reported to be present in 17% of mutant BRAFV600E melanomas with independent stimulatory effects on cell-cycle progression via CDK4." (PMID 21139585, 2011). "We have reported earlier that CYLD by retaining Bcl-3 in the cytoplasm reduces the expression of cyclin-D1 and consequently decreases the proliferation of keratinocytes and melanoma cells." (PMID 21573132, 2011). "Copy number of CyclinD1 (CCND1) gene, a cell cycle mediator, is amplified in 25% of human melanomas." (PMID 22046555, 2011). "Over expression of cyclin D1 plays important roles in the development of human cancers, including breast, melanoma and prostate." (PMID 22168458, 2011). "Significantly, the RREB1 probe, at 60% exhibited the highest sensitivity for melanoma, while the CCND1 probe and MYB probes exhibited significantly lower sensitivities at 38% and 37% respectively." (PMID 21834951, 2011). "Interestingly, the amplification of CCND1 is relatively rare in melanomas with BRAF-NRAS mutations and may have similar effects on melanoma cell growth as the activation of the mitogen-activated protein kinase (MAPK) signaling pathway resulting from BRAF and/or NRAS mutations." (PMID 21911917, 2011). "The MAPK activity drives the uncontrolled growth of melanoma cells by upregulating the expression of cyclin D1 and through the suppression of the cyclin-dependent kinase inhibitor p27KIP1." (PMID 20531415, 2010). "It was noted that PLX4720 also reduced pRB protein phosphorylation, increased p27 expression, suppressed cyclin D1 expression and induced cleavage of PARP only in melanoma cell lines harbouring the BRAF-V600E mutation." (PMID 20531415, 2010). "BRAF controls proliferation of human melanoma cells through the regulation of cyclin D1 and cyclin-dependent kinase inhibitor p27Kip1 protein." (PMID 20485284, 2010). "Additionally, Mcl‐2 and CCND1 are two genes influenced by the downregulation of miR‐193b in melanoma progression." (PMID 39823244, 2025). "This paired model provides a valuable framework for understanding the molecular-genetic changes during the transition from primary to distant metastatic phenotypes; accordingly, our previous findings identified that cyclin D1 is a key factor that drives the distant metastasis of melanoma." (PMID 39948552, 2025). "In addition, CDK4 and CCND1, cell cycle regulators that are frequently mutated or amplified in BRAF wild-type melanomas, were included." (PMID 40647405, 2025). "High-throughput screening and in vitro experiments identified BCL3ANT as a lead molecule that could interfere with Bcl-3-mediated cyclin D1 expression and cell proliferation and migration in melanoma." (PMID 38238702, 2024). "In meningeal cells, exposure to CSF conditioned by melanoma/meningeal cell co-cultures also promoted cyclin D1, fibronectin, TGF-β1, and TGF-βR expression, suggesting that exposure to tumor cells in the CSF space activates pro-tumorigenic, CAF-associated programs in meningeal stroma." (PMID 38866016, 2024). "Additionally, BCL3ANT reduced cyclin D1 luciferase activity in Bcl-3-overexpressing melanoma cells in a concentration-dependent manner." (PMID 38238702, 2024).